IFNG (interferon gamma)
Diseases named in the same sentence as IFNG in open-access papers (continued):
Sharing a sentence is not in itself a finding about the gene and the disease.
viral infection (continued). "Although levamisole induced significant IFNγ secretion in the experiment described in the previous section, levamisole alone did not elicit host defense against viral infection." (PMID 39845058, 2024). "Also, viral infections in mice indicate that DLL1 ligand responses and IFNγ increases play roles in combatting infection." (PMID 38542260, 2024). "Astrocyte effectiveness at initiating T cell responses may be contextual, or even protective in limiting immune responses; curiously, murine astrocytes in a viral infection scenario upregulate both MHC II and PD-L1 in a suppressive response to IFNG." (PMID 39585062, 2024). "In contrast, most of viral infections do not induce PCT synthesis due to the production of interferon-gamma (INF-γ), which inhibits TNF-alpha production and, hence, PCT synthesis." (PMID 39195007, 2024). "The levels of IL-6, IFNγ, IP-10, were significantly decreased at day 4 after viral infection, but not affected by Apta-1 treatment." (PMID 38474386, 2024). "Instead of CD8 T cells, CD4 T cells are critical for controlling viral infection in SGs by secreting TNFα and IFNγ, which act on nonhematopoietic cells." (PMID 39134803, 2024). "On the other hand, ATG5 can also obstruct viral infections by playing a pivotal, non-degradative role in IFNγ-mediated antiviral defenses." (PMID 38915300, 2024). "Redundant functions by type-1 and type-3 IFNs that are induced earlier during the course of viral infection are a potential explanation for lack of IFNγ requirement in these settings." (PMID 38086794, 2023). "Conversely, and despite potential roles for these two BIRCs in cell fate determination during viral infections, the antiviral cytokine, IFNG, did not acutely induce expression of either BIRC2 or BIRC3." (PMID 37289679, 2023). "A significant characteristic of severe viral infections such as SARS and COVID‐19 is a cytokine storm, which involves the release of major inflammatory factors like interleukins, interferon‐gamma (IFN‐gamma), tumor necrosis factor‐α (TNF‐α), and other cytokines." (PMID 38107099, 2023). "CRISPR screening in mock- or IFNγ-treated cells revealed genes essential for cell survival in the absence of viral infection; these were not studied further." (PMID 37905813, 2023). "Moreover, in both control and SZ NPCs, IFNγ treatment activated the canonical JAK-STAT signalling pathway, as would typically be seen in response to viral infection." (PMID 35716830, 2022). "Our finding that M-MDSC isolated from CoV2+ individuals express more p47phox, and ROS neutralization in M-MDSC depleted cultures did not augment IFNγ production in response to the peptide pool of immune dominant S-antigen is similar to other viral infections." (PMID 35812392, 2022). "However, IFNG levels were increased only ~three-fold in G+/− and G+/−GR1−/− cell lines upon viral infection, and IFNGR1 levels remained completely unchanged in infected GR1−/− and G+/−GR1−/− cell lines." (PMID 35897807, 2022). "It potently inhibits the expression of lung cellular anti-viral proteins at baseline and in response to IFNγ in lung epithelial cells, which may facilitate SARS-CoV-2 escape from the host antiviral innate immune response during early viral infection." (PMID 34177923, 2021). "While there is data supporting interactions between Wnt pathways and Type I IFN during viral infections, this has not been explored yet in the context of IFNγ." (PMID 34747695, 2021). "Moreover, the inhibitory effects of baricitinib on interferon-gamma, which has a broad-spectrum antiviral activity at multiple stages, might result in a hypothetical negative impact when added to the analogous effects in the defense against viral infections of IL-6 blockade." (PMID 34820393, 2021). "Thus BAFF-R is differently expressed by TFH during response to a TD Ag or viral infections, and BAFF/BAFF-R interactions on TFH differently regulate IFNγ in autoimmune and infection settings." (PMID 33572146, 2021).
viral infection (continued). "To investigate if multiple vaccinations with TIV can result in detectable NP-specific IFNγ+ CD8+ T cells without the need of a virus infection, we performed an independent repeat experiment that also included a mock challenge control for 3xTIV mice." (PMID 32582220, 2020). "PCT levels are not elevated in viral infections because interferon-gamma, which is produced in viral infections, inhibits PCT production." (PMID 33081061, 2020). "Interferon-gamma activates the Janus kinase/signal transducer and transcription activator (JAK-STAT) pathway and thus allows the transcription of IFN-stimulated genes (ISGs)—many of which are involved in the fight against viral infections." (PMID 32784805, 2020). "Indeed, although type 1 IFN predominantly uses the STAT1 pathway, leading to anti-proliferative effects, viral infection induces predominant STAT4 expression and promotes IFNγ." (PMID 33013883, 2020). "In a pro-Th1 environment, as reported in some viral infections, cytotoxic CD8+ T cells and NK cells may produce ST2L and IFNγ to expand the Th1 response." (PMID 33133101, 2020). "Importantly, many viruses are able to infect professional APCs such as dendritic cells and most cells can upregulate MHCII when stimulated with IFNγ, suggesting that direct endogenous MHCII processing is a common phenomenon during viral infection." (PMID 32745153, 2020). "NKLAM is an interferon-stimulated gene (ISG) as its expression is increased by IFNβ and IFNγ treatment, but the effect of viral infection or viral nucleic acid mimetics on NKLAM expression is not known." (PMID 31539400, 2019). "Analysis of the PBMCs from the highly resistant SIBD01 recipient reveals that the improperly matched allogeneic stem cells induce a detectable IFNγ response even in the absence of virus infection that appears to originate from both NK and T cells." (PMID 30917829, 2019). "Moreover, dendritic cells (DCs) from SJL mice are more permissive to viral infection and viral-induced apoptosis and produce higher levels of IFN-I and IFNγ than DCs from C57BL/6 mice." (PMID 30669615, 2019). "CXCL10 is secreted by monocytes, endothelium, and fibroblasts after IFN-γ (interferon gamma) stimulation in response to viral infection, and after LPS stimulation in response to Gram-negative infection." (PMID 29661181, 2018). "While these data clearly show a role for IFNγ in the mortality to an otherwise nonlethal viral infection, the direct contribution of Tregs is less clear." (PMID 30042764, 2018). "This cytokine mode of activation may be a useful tool for the immune system in the context of viral infection where IL-12 and IL-18 are induced, and MAIT cell production of IFNγ in the local milieu can have direct antiviral effects." (PMID 28742082, 2017). "Since direct viral infection cannot account for NSPC loss in our model system, one possibility is that the cytokine milieu that is released in the absence of IFNγ is ultimately detrimental to the cells." (PMID 27178303, 2016). "IFNγ is the canonical Th1 cytokine that is crucial for a cellular immune response as it controls the differentiation of naïve CD4+ T cells into Th1 effectors, which mediate cellular immunity against viral infections." (PMID 26653678, 2016). "The ability of IFNγ, but not TNFα, to inhibit virus infection was also demonstrated in human macrophages." (PMID 26562011, 2015). "A recent in vitro analysis showed significant ADAR genotype (and haplotype)-dependent modulation of IFNγ-producing cells (or IFNγ-Elispot responses upon viral infection) in CAs but not in AAs." (PMID 25868721, 2015). "IFNγ treatment of BALB/c or C57BL/6 IFNAR-/- macrophages inhibited virus infection, indicating that IFNγ does not require the presence of a functional type I IFN receptor for its antiviral effect." (PMID 26562011, 2015).
viral infection (continued). "In view of these considerations, and to explore the tumor-related changes that may potentially influence the innate immune response to virus infection, KOS and JD0G viral replication in glioblastoma cells were tested for their sensitivity to IFNγ treatment." (PMID 22924042, 2012). "In summary, these data indicate a highly specific response of macrophages through a coordinated negative regulation of multiple sterol pathway members upon viral infection or treatment with IFNγ or β but not IL1β, TNF, or IL6." (PMID 21408089, 2011). "Second, PyV infection i.p. activated NK and γδ T cells to produce IFNγ as did PyVTu injection, but in contrast to PyVTu cells, the viral infection did not lead to high levels of granzyme-B production." (PMID 20523894, 2010). "In this population-based study, we found nine genes/regions associated with CIN3/cancer, 6 of which remained significant at a FDR≤0.2 – three DNA repair genes (GTF2H4, DUT, and DMC1) and three viral infection and cell entry related genes (OAS3, SULF1, and IFNG)." (PMID 20084279, 2010). "The naive SMARTA cells did not produce IFNγ immediately after virus infection, nor did they undergo cell division." (PMID 18404208, 2008). "Therefore, the increased TNF-α, IFNγ, NF-κB, and iNOS immunoexpression observed in the SARS-CoV-2-infected seminiferous epithelium confirms a pro-inflammatory response of this epithelium to the viral infection." (PMID 41596343, 2026). "While type II interferon (IFNγ) plays a crucial role in controlling intracellular pathogens and regulating tumor suppressor genes, type I (including IFNα, IFNβ, IFNω) and type III (IFNλ) interferons are the classic antiviral cytokines, triggering the expression of ISGs that combat viral infections." (PMID 41472304, 2025). "Therefore, we wanted to examine whether different cellular stress conditions, including FCS starvation, IFNγ treatment, TNF treatment, viral infection (LCMV) and heat-shock, lead to enhanced DRiP formation in our set-up." (PMID 39247192, 2024). "Upon viral infection, IFN‐α/β and IFNγ activated NK cells to provide early antiviral responses, followed by clonal expansion and differentiation of naïve (N) CD8+ T cells into effector (E) populations on basis of adaptive immune responses against viral infection." (PMID 38992867, 2024). "Here, using an IFNγ-YFP reporter system to identify CD8+ T cells executing antigen-dependent effector functions, we define the transcriptional consequences and functional mechanisms controlled by TCR-signaling strength that occur within the skin during viral infection to promote TRM differentiation." (PMID 37402742, 2023). "To determine whether the virus infection of glioma cells subsequently induced an immunostimulatory boost aside from the induction of ICD, we measured the release of IFNγ in cocultures of virus-infected glioma cells and HLA-matched PBMCs, the latter being unaffected by the infection with XVir-N-31." (PMID 36077380, 2022). "Interestingly, survival curve analysis suggested that Ifnγ−/− mice developed symptoms earlier than WT mice upon viral infection, but no significant changes were observed in survival time." (PMID 34379515, 2021). "Given that IFNγ, IL-1β and TNFα are upregulated by PBMC following co-culture with S. thermophilus 285 this suggests that S. thermophilus 285 induces powerful defense against invading pathogens and could be beneficial against virus infection and tumours." (PMID 32045425, 2020). "This may suggest that the increase in the number of ASFV-specific IFNγ secreting cells between day 59 and 66 is, in fact, a primary response to viral infection, rather than a secondary response to the immunization regime." (PMID 32443536, 2020). "However, we observed that LUBAC overexpression did not significantly affect the production of basal levels of all three types of IFN (IFNɑ, IFNγ, and IFNλ) in cells without viral infection." (PMID 32123171, 2020).
viral infection (continued). "IKBKB, IFNG and PDGF BB are other proteins that have been shown to be involved in reactive gliosis, inflammation, cellular plasticity, neurogenesis, protection against autoimmune demyelination, and activation of astrocytes, especially during certain viral infections such as HIV-1." (PMID 32225060, 2020). "Interestingly, although Egr2/3−/− OT-II PD-1high MP cells failed to expand in response to viral infection, more of them produced IFNγ than their wild-type counterparts." (PMID 32709717, 2020). "Thus, Ido2 expression is responsive to peripheral immune-cell-derived IFNγ (resident cells in the brain do not produce IFNγ) and bacterial or viral infections (via LPS or dsRNA) but relatively unaffected by stress hormones." (PMID 27142940, 2016). "Considering that both IFNγ and IFN-I are generally thought of as antiviral and immune stimulatory during viral infection, our data now provide a new mechanistic understanding that integrally links inflammation to balance immunosuppression during persistent virus infections." (PMID 26808628, 2016). "In time-series experiments profiling genome-wide lipid-associated gene expression of macrophages, we show a selective and coordinated negative regulation of the complete sterol pathway upon viral infection or cytokine treatment with IFNγ or β but not TNF, IL1β, or IL6." (PMID 21408089, 2011). "It is interesting that IFNγ augmented responses to multiple contractile agents suggesting that this cytokine could have a key role in AHR development during e.g. viral infection and in asthma per se as CD8+IFNγ + cell numbers in the airways of asthma subjects correlate with AHR." (PMID 17903241, 2007). "Thus, CD40 induction in PMVECs depends on IFNγ rather than direct viral infection." (PMID 41542053, 2026). "Interestingly, SARS-CoV-2-only infected mice maintain terms representative of an active viral infection; however, they do not show enrichment in “leukocyte chemotaxis”, “chemokine production” and “cellular response to interferon gamma”, as seen in the coinfected group." (PMID 38932155, 2024). "Thus, based on the fact that we could not observe a virus-induced induction of FAT10 expression in A549 cells, we speculate that the inflammatory microenvironment that accompanies the viral infection in vivo (which includes TNF and IFNγ) stimulates FAT10 expression." (PMID 37940187, 2024). "We found that genes related to virus entry, virus replication and suppression of interferon-gamma signaling are all up-regulated in failing CMs, and the increase was significantly higher in ACE2+ CMs, suggesting that these CMs may be more vulnerable to virus infection." (PMID 33718452, 2021). "Interestingly, infection with both viruses markedly promoted the expression of TLR1 and TLR2, which are sensors of bacterial components, which may be explained by the up-regulation of IFNα and IFNγ that could enhance the expression of TLR1, TLR2, TLR3, and TLR7 in viral infections." (PMID 27916934, 2016). "Differences in circulating IFNγ secreting cells did not account for differences in age-dependent infection; rather, they suggested that finishers were more similar to piglets, a conclusion that is in contrast to the similarity between finishers and sows in control of viral infection." (PMID 19860914, 2009). "During acute viral infection, absence of SPP in the eye did not affect CD4 expression but did affect CD8α and IFNγ expression in the eye." (PMID 36215312, 2022). "During viral infection, human BM-MSCs do not inhibit cytotoxic T lymphocyte (CTL) functions, but rather facilitate CTL responses by releasing interferon-gamma (IFN-γ)." (PMID 32850818, 2020). "IFNγ expression was not significantly different compared to the ORI group, which is not surprising since these patients were suffering from other respiratory infections, which, in most cases, were viral infections." (PMID 38474725, 2024).
viral infection (continued). "Indeed, in LNCaP-JAK1 cells, IFNγ activated STAT1 but not STAT3, abrogated NS3 production in EHDV-TAU-infected cells, and supported oncolysis by non-productive viral infection." (PMID 29441069, 2018). "Thus, unlike lungs, where IFNγ was essential to stimulate IDO activity during and after infection, redundant IFN type I or type II signals up-regulated IDO activity in msLNs during viral infection." (PMID 23785507, 2013).
tuberculosis (1,086 papers, 2004 to 2026). A chronic, recurrent infection caused by the bacterium Mycobacterium tuberculosis. "Beyond conventional diagnostic approaches, interferon-gamma release assays (IGRAs), such as Quantiferon TB Gold, have been increasingly recognized as valuable tools in tuberculosis, not only for diagnosis but also with potential prognostic implications." (PMID 41149052, 2025). "Severe defects in human IFNγ immunity predispose individuals to both Bacillus Calmette–Guérin disease and tuberculosis, whereas milder defects predispose only to tuberculosis." (PMID 39198650, 2024). "Interferon gamma release assays (IGRAs) are in vitro diagnostic assays that assist in the diagnosis of tuberculosis by detecting the release of specific IFN-γ in blood samples." (PMID 37848021, 2023). "Aging and DM act synergistically to lower interferon-gamma, which increases susceptibility to tuberculosis, for which cell-mediated immunity is crucial." (PMID 38058320, 2023). "In order to investigate the association between +874 A/T SNP of IFNG and tuberculosis population in Argentina, genomic DNA extracted from whole blood and oral swabs in nucleic acid paper was genotyped by ARMS-PCR as described in Material and Methods." (PMID 36743307, 2023). "The tuberculin skin test (TST) and the interferon-gamma release assay (IGRA) test are two currently available indirect diagnostic techniques used for the diagnosis of tuberculosis." (PMID 36288019, 2022). "Researchers described a new paper based electrochemical impedance biosensor for label-free detection and quantification of human interferon-gamma (IFN-γ), a biomarker which plays an important role in tuberculosis susceptibility." (PMID 36418852, 2022). "Higher levels of interferon-gamma were associated with increased risk of progression to active tuberculosis." (PMID 34022827, 2021). "tuberculosis in mice exposed tobroad-spectrum antibiotics exposure was associated with decreasedproportions of IFNγ+ and TNF+ CD4+ T cellsalongside an increased percentage FoxP3-positive Treg cells in the spleen." (PMID 33857251, 2021). "Interferon-gamma (IFN-γ) release assay should be also performed in patients with risk factors for tuberculosis such as immigrants, low socioeconomical status, and endemic countries." (PMID 32230730, 2020). "In fact, OR were calculated to estimate the level of association between the IFNG rs1861494 genotypes and tuberculosis disease by logistic regression after adjusting for confounding variables." (PMID 29361774, 2018). "The diversity of policies across countries calls for more research in how to use interferon-gamma release assay and tuberculin skin testing together among different risk groups based on the underlying tuberculosis epidemiology." (PMID 29531416, 2018). "In order to investigate the association between the IFNG rs1861494 SNP and tuberculosis in Argentina, 175 HD and 201 TB were recruited between 2014 and 2017." (PMID 29361774, 2018). "In BCG-vaccinated infants, higher abundance of cells releasing IFNγ upon BCG stimulation was associated with lower risk of progression to tuberculosis disease." (PMID 29028973, 2018). "Nevertheless, our results are in agreement with a study performed in Iran, a population ethnically different from ours, further supporting the fact of a higher resistance to tuberculosis disease in individuals carrying the A allele of the IFNG rs1861494 SNP." (PMID 29361774, 2018). "Until now, there are no studies in the Argentinean population analyzing the association between an IFNG SNP and tuberculosis." (PMID 29361774, 2018). "Significantly positive, decreased, and protective associations were found between the IFNG +874 T/A(rs2430561)polymorphism and tuberculosis risk in five genetic models." (PMID 28881572, 2017).